INS (insulin)
Diseases named in the same sentence as INS in open-access papers (continued):
Sharing a sentence is not in itself a finding about the gene and the disease.
Hyperglycemia (continued). "Here, we show that BL001, a small LRH-1 agonist, impedes hyperglycemia progression and the immune-dependent inflammation of pancreas in murine models of T1DM, and beta cell apoptosis in islets of type 2 diabetic patients, while increasing beta cell mass and insulin secretion." (PMID 29662071, 2018). "We found that STZ induced type 1 diabetes (hyperglycemia and lack of insulin) in rats." (PMID 30524676, 2018). "Any reduction of hyperglycemia by both diets is not due to changes in insulin secretion." (PMID 30619502, 2018). "Third, we did not investigate the effect of insulin treatment on patients with hyperglycemia." (PMID 30082824, 2018). "Unlike insulin-producing ß cells that are destroyed in type 1 diabetes, not only are α cells preserved but become hyperplastic with inappropriately high circulating plasma glucagon that substantially contribute to the hyperglycaemia of this disorder." (PMID 30228292, 2018). "Skeletal muscle insulin sensitivity is not measured in the clinic since it is impractical and because it is the exposure to persistent hyperglycemia (in additional to elevated lipids and inflammatory cytokines) that elicits diabetic complications and cardiovascular mortality." (PMID 30061841, 2018). "The insulin immunoreactivity in islets was decreased, and the average islet volume was significantly increased (F = 11.246, P < 0.01; post hoc analysis revealed that both CRS-hyperglycemia and CRS-normoglycemia group were significantly different from the control, P < 0.01)." (PMID 30618599, 2018). "However, the presence of hyperglycemia and hypoglycemia in boys with normal or low body mass index suggests that the dystrophy state, and not just body composition, alters insulin sensitivity in DMD." (PMID 29508262, 2018). "Hyperglycemia should be treated with insulin, not with a decreasing glucose intake." (PMID 29926323, 2018). "Several studies have speculated that hyperglycemia may be conferred by changes in LRP5 expression levels or tissue expression specificity, since LRP5 signaling contributes to the glucose-induced insulin secretion in the islets of Langerhans, however this mechanism is unclear." (PMID 30304114, 2018). "Moreover, STZ-mediated hyperglycemia did not allow an analysis of the effects of carnosine on β-cell function, since the insulin-producing cells were eliminated." (PMID 28281693, 2017). "No, sufficient levels of basal insulin must be present to prevent hyperglycemia." (PMID 28323959, 2017). "Indeed, 2 weeks after STZ injection, DIO/STZ mice developed fasting hyperglycaemia, profound glucose intolerance and decreased plasma insulin levels during ipGTT compared to non-STZ treated mice." (PMID 28740254, 2017). "Sodium-glucose cotransporter 2 (SGLT2) inhibitors are antidiabetic agents that correct hyperglycemia by promoting urinary excretion through the inhibition of glucose reabsorption in proximal tubules irrespective of the patient’s insulin secretory capacity or insulin resistance." (PMID 28391776, 2017). "In the NDF35 group, the effect of STZ (35mg/kg bw) could possibly have been compensated by the normal defense homeostasis mechanisms, unlike the FDF35 group which were already insulin resistant presenting mild hyperglycaemia." (PMID 28129400, 2017). "In the absence of overt hyperglycaemia, maternal insulin and triglycerides may signal increased placental transport of fatty acids leading ultimately to macrosomia." (PMID 28570613, 2017). "Based on these results, control of hyperglycemia by treatment of insulin may not be enough for preventing renal fibrosis after IRI, and further studies on the effect of other hypoglycemic agents with different action mechanism on tubular cells, are necessary." (PMID 29196746, 2017).
Hyperglycemia (continued). "For our patient, who did not respond even to low- and moderate-intensity exercise, we discouraged preexercise insulin dose reductions to avoid severe hyperglycemia and to minimize any negative impact of regular periexercise hyperglycemia on long-term glycemic control." (PMID 28662684, 2017). "One is that although FAM3C activates HSF1-CaM pathway to activate Akt independent of insulin in cultured hepatocytes, whether it can suppress hepatic gluconeogenesis to improve hyperglycemia of type 1 diabetic mice remains unknown." (PMID 29285313, 2017). "Thus, hyperglycaemia should be treated by reducing the glucose intake to 2.0 g/kg/day, and up to 4 IU/h insulin, if needed, to maintain euglycaemia because higher insulin doses do not improve glucose oxidation." (PMID 29035319, 2017). "Conversely, mice lacking miRNA 375 have low insulin synthesis and hyperglycemia." (PMID 28574454, 2017). "The biggest impact was seen on hyperglycemia for nonusers of insulin." (PMID 28698167, 2017). "The character in DM is a relative or absolute lack of insulin, resulting in hyperglycemia." (PMID 28612706, 2017). "Interestingly, cancer patients treated with HDAC inhibitors develop hyperglycemia as a side effect, suggesting that HDAC inhibition may reduce insulin signaling in some organs." (PMID 28886131, 2017). "In fact, using a simple analogy, increased beta power in poor motor function may be similar to increased insulin levels in hyperglycemia (insulin does not lead to increased glycemic levels but rather tries to compensate)." (PMID 28539912, 2017). "Oral administration of CA (approximately 17 mg/kg/day) to obese leptin receptor deficient mice for five weeks resulted in significant protection against fat-induced fasting and non-fasting hyperglycemia, improved glucose tolerance as well as decreased serum insulin levels." (PMID 28862678, 2017). "However, the effect of chronic HBV infection on human insulin sensitivity and hyperglycemia is not consistent in the literature." (PMID 28852048, 2017). "However, GENS group dramatically decreased insulin and TG level in blood serum, indicating that GENS may efficiently ameliorate HFD-induced hyperglycemia in these animals." (PMID 28358328, 2017). "Negative result with insulin treatment could be anticipated, because the correction of hyperglycemia might be suboptimal in our experiment (mean HgA1c 6.5%) or ischaemic kidney damage in diabetic group was too severe to overcome with the blood glucose control." (PMID 29196746, 2017). "Furthermore, they imply that early exogenous insulin therapy has no suppressive effect on the ability of beta-cells to secrete c-peptide (and therefore insulin) during stress-hyperglycemia." (PMID 28497374, 2017). "In fact, “rebound hyperglycemia” could be produced when the SQ Lispro insulin dose exceeded 6 U (data not shown)." (PMID 26819233, 2016). "In addition, it stimulates insulin release from pancreas, for THIO could be used to treat postprandial hyperglycemia and protect against diabetic complications." (PMID 27051452, 2016). "We report that the absence of hyperglycemia observed in glucagon-deficient mice after STZ treatment can be explained through the persistence of a residual β-cell mass, which ensures a low level of insulin action." (PMID 27092792, 2016). "Despite the lack of a clear mechanism by which hyperglycemia causes elevated IOP, insulin resistance might provide an explanation for previous studies." (PMID 27977733, 2016). "Since insulin inhibits the activity of Glc-6-Pase in the liver of STZ induced diabetic rats and controls hepatic glucose production (HGP), the insulinotropic effect of PL extract might play a crucial role in the control of hyperglycemia in STZ diabetic rats." (PMID 26942038, 2016). "A rapid non-invasive sensitive screening tool that rules out DKA in patients with severe hyperglycaemia may avoid unnecessary administration of insulin infusion as part of initial therapy." (PMID 26821648, 2016).
Hyperglycemia (continued). "Upon consumption of a meal, the ability to dispose of the absorbed glucose, and thus minimize postprandial hyperglycemia and its potentially negative consequences, is dependent on the subject’s pancreatic responsiveness, insulin sensitivity and glucose effectiveness." (PMID 27253712, 2016). "While insulin is not harmful in severe hyperglycemia, patients may achieve euglycaemia with fluid resuscitation alone and an insulin drip is not needed." (PMID 26821648, 2016). "In addition, a substantial number of persons without pretransplant DM had hyperglycemia and required insulin during the hospital phase of their care and had to be discharged on insulin." (PMID 28031946, 2016). "In patients with BGL ≥10 mmol/l, ketosis resolved within 3–4 days irrespective of whether insulin was administered or not and despite persistent hyperglycemia according to protocol." (PMID 27633987, 2016). "Hyperglycemia and Adverse Pregnancy Outcome (HAPO) study confirmed the link between maternal glucose and neonatal adiposity and suggested that the relationship might be mediated by fetal insulin production." (PMID 27741952, 2016). "Because it cannot be known at hospitalization what proportion of patients without pretransplant DM will resolve their hyperglycemia or will continue to require insulin after discharge, all these patients need ongoing education and support regarding hyperglycemia management." (PMID 28031946, 2016). "Interestingly, total insulin levels in the circulation were not frankly low in Akita mice, although they did not rise appropriately with the onset of hyperglycemia." (PMID 28702245, 2016). "Moreover, in 2–4 week-old Akita mice, neither circulating insulin nor circulating C-peptide rose above wild-type levels despite the development of hyperglycemia that should stimulate increased insulin secretion." (PMID 28702245, 2016). "The continuous insulin infusion during CPB should ideally have prevented high blood glucose levels, however, the release of stress hormones due to surgical stress resulted in insulin resistance, leading to prolonged hyperglycemia (Lehot, Piriz, Villard, Cohen & Guidollet, 1992)." (PMID 27157174, 2016). "These neuropathic changes developed without overt fasting hyperglycemia in 18 month old GK rats (control = 3.2 ± 0.4 mM and GK = 4.4 ± 1.3 mM) and the authors suggest that these changes appear to be more related to the decrease in neuronal insulin support." (PMID 28066166, 2016). "The degree of hyperglycemia was similar among the DM patients regardless of whether insulin was used pretransplant." (PMID 28031946, 2016). "Furthermore, TUDCA effectively deceased body weight, fasting blood glucose, and serum insulin levels in HFD-treated mice, demonstrating an important role for ER stress in enhancement of hepatic gluconeogenesis-mediated fasting hyperglycemia in HFD-treated mouse." (PMID 28029143, 2016). "The lacks of our study are that we have not measured leptin and insulin levels, but hyperglycemia was observed in the EV-induced PCOS animal model, which it may be due to the increase in sympathetic activity." (PMID 26577050, 2015). "Several studies have demonstrated that taurine supplementation has potential as a regulator of insulin secretion and promotes insulin sensitivity; moreover, taurine can ameliorate fructose-induced hyperglycemia, hypertension and hepatic steotosis in pregnant and non-pregnant rats." (PMID 26561832, 2015). "This implies that hyperglycemia, which is harmful to diabetic patients, activates Akt and inhibits autophagy and apoptosis like insulin, but this effect is independent of the insulin level." (PMID 26060824, 2015). "Models presenting a more mild diabetic condition, defined as moderate hyperglycemia, with fasting plasma glucose of approximately 10–15 mmol/L and positive energy balance without exogenous insulin requirement could be relevant in long-term studies." (PMID 26394837, 2015).
Hyperglycemia (continued). "In the present study, we tested the hypothesis that miR-15b and miR-16 levels are altered by exposure to hyperglycemia in REC, and that miR-15b/16 play key roles in regulating insulin signaling through a reduction in TNFα- and SOCS3-mediated insulin resistance pathways." (PMID 25888955, 2015). "However, it was surprising that control of hyperglycemia with insulin did not attenuate the development of renal cortical fibrosis or the formation of tubular casts which is an index of tubular necrosis." (PMID 26169541, 2015). "Changes in the transport of glucose to the brain during extreme hyperglycemia occur with no changes in the expression of insulin-sensitive mRNA or insulin insensitive transporters, while at the protein level insulin-insensitive glucose transporter GLUT1 is downregulated." (PMID 26528968, 2015). "Thus, although activation of LXRs increased lipogenesis, it does not affect its role in the improvement of hyperglycemia and insulin sensitivity." (PMID 25909991, 2015). "Indeed, our finding that control of hyperglycemia with luseogliflozin which did not increase plasma insulin levels, did reduce the degree of tubular necrosis is consistent with this view." (PMID 26169541, 2015). "Clinical practice guidelines have recommended the use of insulin regimen with combined basal and short or rapid-acting insulin (basal bolus approach) as the preferred insulin regimen for the management of hyperglycemia in hospitalized patients in non-critical care setting." (PMID 26697118, 2015). "The results show that levels of serum insulin, glucose, triglyceride, and free fatty acid were significantly decreased in VA-treated HFD rats (p < 0.05), indicating the protective effects of VA against hyperinsulinemia, hyperglycemia and hyperlipidemia in HFD rats." (PMID 26633482, 2015). "A direct comparison of P5 with the reference peptide Ex4 revealed that G-protein signalling downstream of GLP-1R activation in the absence of β-arrestin signalling is sufficient to correct hyperglycaemia, improve insulin sensitivity, preserve pancreatic islet integrity and improve liver steatosis." (PMID 26621478, 2015). "In nondiabetics, the hyperglycemia was maximum after first pulse and returned to baseline with subsequent pulses, but diabetic patients had cumulative effects of the hyperglycemia with repeated pulses, and a quarter of the diabetic patients required insulin." (PMID 26681940, 2015). "Both pancreas insulin secretion and peripheral insulin responsiveness are well-functioning in the correction of hyperglycemia states, so it is reasonable to understand the absence of effects of curcumin in the glucose tolerance and in the insulin sensitivity of nondiabetic rats." (PMID 26064170, 2015). "In this study, dietary intake of genistein (250 mg/kg bw) improved hyperglycemia, glucose tolerance, and blood insulin level in obese diabetic mice, whereas it did not affect body weight gain, food intake, fat deposit, plasma lipid profile, and peripheral insulin sensitivity." (PMID 26705405, 2015). "Thus, hyperglycemia induces HSPG degradation or inhibits its synthesis (likely due to EC injury), and insulin may have a direct protective effect on the endothelium, independent of its blood glucose-lowering effect." (PMID 26448756, 2015). "However, the mechanism by which baicalein treatment ameliorates fasting hyperglycemia is unclear, given that neither fasting plasma insulin levels nor peripheral insulin sensitivity was significantly modulated." (PMID 25147566, 2014). "Thus, insulin-induced TD26 and consequent β-cell proliferation and insulin production would not cease under hyperglycemia." (PMID 25530616, 2014). "However, it has been previously reported that obese subjects exhibit blunted GH responses to insulin-induced hypoglycemia or hyperglycemia as compared to the nonobese individuals." (PMID 24966876, 2014).
Hyperglycemia (continued). "Thus, the two insulin types seem not to differ in their effect on HbA1c decline with respect to the type of hyperglycemia." (PMID 23880900, 2014). "However, gastrointestinal glucose absorption is the same in patients with T2DM and healthy subjects Basal insulin may restrict the glycogen output by decreasing both pre-meal blood glucose and FBG levels and partially restraining postprandial hyperglycemia." (PMID 25187822, 2014). "Islet transplantation without insulin treatment did not reverse hyperglycemia." (PMID 24743240, 2014). "The administration of basal insulin with or without metformin decreases the fasting glucose level and the overall glycemic profile, but in our cases, it was insufficient to postprandial hyperglycemia in 15 of the 16 cases." (PMID 24684803, 2014). "JCR:LA-cp rats do not develop hyperglycemia, due to islet β-cell insulin hypersecretion." (PMID 24809394, 2014). "However, insulin therapy failed to maintain normoglycaemia consistently throughout the 4-week period, and sporadic episodes of hypoglycaemia (<2 mM) and hyperglycaemia (>20 mM) were common." (PMID 25145789, 2014). "Furthermore, selective hepatic insulin resistance is observed in patients with T2DM, where insulin fails to inhibit glucose production and maintains lipogenesis, contributing to, and exacerbating hyperglycaemia and hyperlipidaemia." (PMID 24408966, 2014). "It was also reported before that the hyperglycemia in T1BDM in humans developed due to the presence of dermcidin could be controlled by stimulating the systemic NO synthesis without using external insulin administration." (PMID 24711743, 2014). "Interestingly, 24 h hyperglycemia (but not hypoglycemia) significantly increased the expression of insulin-responsive GLUT-4." (PMID 24708805, 2014). "Our findings indicate that other mechanisms besides hyperglycemia or lack of insulin also may stimulate islet cell remodeling in diabetic animals." (PMID 25101835, 2014). "Reversal of hyperglycemia by administering insulin improved the influx of humoral immune components to the site of infection at 24 hours after infection compared with animals that did not receive insulin." (PMID 25610878, 2014). "One notable observation is that miR-133a–mediated attenuation of fibrosis occurred even without reversal of hyperglycaemia, which indicates that miR-133a could also become a therapeutic target along with or without insulin for treating diabetic patients." (PMID 24428157, 2014). "GHR-KO;RIP::IGF-1 mice are capable of inducing a greater transcriptional (or possibly translational, but probably not simply secretory) insulin action response to hyperglycemia than standard GHR-KO mice when challenged with a glucose load under AL-fed conditions." (PMID 25244225, 2014). "These mice (gckw/– mice) were used to investigate the functional and structural changes in the myocardium that result from long-term (60 weeks) reduced liver gck expression (yielding mild hyperglycemia) followed by 4 weeks with or without treatment with insulin or rosiglitazone." (PMID 24447392, 2014). "The presence of hyperglycemia or hypoinsulinemia did not seem to explain the difference in islet remodeling between the two models given that insulin replacement by insulin implant or islet transplantation in STZ-diabetic mice did not prevent alpha-cell expansion." (PMID 25101835, 2014). "We hypothesized that short-term hyperglycemia by lowered insulin treatment as opposed to normoglycemia would have detrimental effects on left ventricular contractile function in T2D patients." (PMID 23308171, 2013). "We found that hyperglycemia enhanced inflammatory responses in the acutely injured lung and that inhaled insulin ameliorated these responses, as shown in reduction of IL-8 and TLR4 mRNA expressions in the BALF cells, even greater than those treated by intravenous insulin." (PMID 23622115, 2013).